GALC (galactosylceramidase)
Diseases named in the same sentence as GALC in open-access papers (continued):
Sharing a sentence is not in itself a finding about the gene and the disease.
dementia (2 papers, 2018 to 2020). Loss of intellectual abilities interfering with an individual's social and occupational functions. "However, genetic studies in late-onset KD patients has provided some evidence that reduced GALC enzymatic activity can result in delayed and moderate neuropathology, with moderate development of dementia and neurodegeneration." (PMID 29481565, 2018).
demyelination (2 papers, 2015 to 2022). "In this study, we showed that GALC has a neuron-autonomous role, and its absence in neurons triggers neuro-axonal degeneration and subsequent inflammatory demyelination by affecting other brain cells." (PMID 35789331, 2022). "To address the in vivo relevance of MSC effects on oligodendrocyte survival, we administered MSCs to mice undergoing cuprizone-mediated demyelination and evaluated the survival of galactocerebroside (GalC)+ oligodendrocytes from the corpus callosum." (PMID 26407166, 2015).
glaucoma (2 papers, 2011 to 2015). Increased pressure in the eyeball due to obstruction of the outflow of aqueous humor. "Further studies are warranted on the role of GALC in optic nerve function, the impact of GALC mutations in pathogenesis of glaucoma, and galactosylceramidase activity as a biomarker and a potential therapeutic target for POAG." (PMID 22073273, 2011). "This examination will provide direct evidence to the functional involvement of GALC in the pathogenesis of glaucoma." (PMID 22073273, 2011).
ovarian carcinoma (2 papers, 2010 to 2021). A malignant neoplasm originating from the surface ovarian epithelium. "Survival analysis showed that the high levels of SPHK1, KDSR, SMPD1, GALC, SMPD2, UGCG and DEGS1 were associated with poor prognosis of OS in patients with ovarian cancer, among which DEGS1 was the most significant (P = 3E-04)." (PMID 34488809, 2021).
Sandhoff disease (2 papers, 2019 to 2025). A lysosomal disorder from the GM2 gangliosidosis family, caused by biallelic pathogenic variants in the HEXB gene, characterized by GM2 ganglioside accumulation in the nervous system and progressive central nervous system degeneration. "Two patients carrying known pathogenetic GALC variants were also heterozygous for other known pathogenetic variants in other LSD‐associated genes, including HEXB (Sandhoff disease) and GUSB (mucopolysaccharidosis VI)." (PMID 40391866, 2025).
Skin Cutaneous Melanoma (2 papers, 2023 to 2024). "Data mining was performed on the cBioPortal for Cancer Genomics platform (TCGA Skin Cutaneous Melanoma, Firehose legacy, PanCancer Atlas) to identify those genes whose expression was negatively correlated with GALC expression in 472 human skin melanoma specimens." (PMID 38474307, 2024).
Tremor (2 papers, 2020 to 2025). An unintentional, oscillating to-and-fro muscle movement about a joint axis. "In a 57 year-old male (HA120) affected by ataxic gait, aphasia, tremor, progressive cerebellar dysfunction, three already reported GALC variant were assessed." (PMID 40208338, 2025).
Alzheimer disease (1 paper, 2021). A progressive, neurodegenerative disease characterized by loss of function and death of nerve cells in several areas of the brain leading to loss of cognitive function such as memory and language. "Indeed, alteration of GALC activity was also described by our group in the plasma of patients affected by Mild Cognitive Impairment compared to Alzheimer’s disease patients." (PMID 34572266, 2021).
Angelman syndrome (1 paper, 2024). A neurogenetic disorder characterized by severe intellectual deficit and distinct facial dysmorphic features. "In addition to Angelman syndrome, whole-exome sequencing and CNV analyses identified a compound heterozygous variant in the GALC gene; moreover, a significant decrease was observed in galactose cerebrosidase activity." (PMID 38610036, 2024).
autoimmune diseases of the nervous system (1 paper, 2025). "Reports of inflammation in KD and the association of heterozygous GALC pathogenetic variants with autoimmune diseases of the nervous system, such as MS, support this hypothesis." (PMID 40391866, 2025).
cortical atrophy (1 paper, 2024). "LOKD patients can lack the typical hallmarks in magnetic resonance imaging, like cortical atrophy and white matter changes, which makes reliable tests of enzymatic activity more important in order to confirm pathogenicity of GALC variants." (PMID 38837642, 2024).
folate deficiency (1 paper, 2019). A nutritional condition produced by a deficiency of FOLIC ACID in the diet. "Thirdly, genes with an opposite expression pattern in folate deficiency and repletion cell lines: SORBS2, DCN, SLFN11, RUNX3, GALC, and HSPB7." (PMID 30836646, 2019).
head and neck cancer (1 paper, 2021). A primary or metastatic malignant neoplasm affecting the head and neck. "Recently, downregulation of the GALC gene has been observed in lung and head and neck cancer cells, which can be mediated via hypermethylation of its promoter." (PMID 34502101, 2021).
ichthyosis (1 paper, 2025). Disorders of cornification that are characterized by visible scaling and/or hyperkeratosis of most or all of the skin. "Ichthyosis-like lesions have been reported in another individual with KD; they are likely due to impaired ceramide synthesis in the skin caused by the galactosylceramidase enzymatic deficit that underlies KD." (PMID 41463122, 2025).
keloid (1 paper, 2023). An irregularly shaped, elevated mark on the skin caused by deposits of excessive amounts of collagen during wound healing. "We explored the potential role of GSL metabolism pathway in keloid, classfied keloids based on GSLMRGs expression patterns, provided a set of gene markers including GLTP, GALC, ARSA, HEXB, SUMF2, and GBA2, and constructed a diagnostic model for keloid." (PMID 37168863, 2023). "A strong correlation between IL-7 and GLTP, GALC, ARSA, HEXB, and SUMF2 was found, suggesting that IL-7-based inflammatory factors may involve in keloid growth and development through associating with the GSL metabolism pathway." (PMID 37168863, 2023). "In this study, the differential GSLMRGs of keloid and the top ten genes with the highest importance from machine learning algorithms Random Forest and SVM-RFE were intersected, and six candidate GSLMRGs were identified: ARSA, GBA2, SUMF2, GLTP, GALC, and HEXB." (PMID 37168863, 2023).
lysosomal lipid storage disorder (1 paper, 2025). An inherited metabolic disorder in which harmful amounts of lipids accumulate in cells and tissues. "Mutations in GALC, which encodes galactocerebrosidase, cause Krabbe disease, a lysosomal lipid storage disorder characterized by the accumulation of psychosine (galactosylsphingosine)." (PMID 40498021, 2025).
male infertility (1 paper, 2014). The inability of the male to effect fertilization of an ovum after a specified period of unprotected intercourse. "The data that we have described demonstrate that the altered lipid metabolism, due to GALC deficiency, is not the only cause of male infertility." (PMID 24432014, 2014).
non-small cell lung carcinoma (1 paper, 2025). A group of at least three distinct histological types of lung cancer, including non-small cell squamous cell carcinoma, adenocarcinoma, and large cell carcinoma. "GALC expression in circulating tumor cells is significantly associated with distant metastasis, tumor burden, and treatment-related adverse events in non-small cell lung cancer." (PMID 40069781, 2025).
type 1 diabetes (1 paper, 2018). "For six genes (ORMDL3, GALC, SPHK2, SLC1A5, PPARD and B4GALT1) the SNPs with the strongest association with type 1 diabetes (lowest p value) also acted as cis-eQTLs, suggesting that these SNPs regulate the expression of their associated genes." (PMID 29671030, 2018). "Next, we discovered eight gene polymorphisms (ORMDL3, SPHK2, B4GALNT1, SLC1A5, GALC, PPARD, PPARG and B4GALT1) involved in sphingolipid metabolism that contribute to the genetic predisposition to type 1 diabetes." (PMID 29671030, 2018).
viral infection (1 paper, 2015). "In both cases, viral infection is associated with a dramatic reduction in GalC expression." (PMID 26733813, 2015).
Werdnig-Hoffman disease (1 paper, 2022). "We note that the causative gene for Werdnig-Hoffman disease is survival motor neuron 1 (SMN1) and that for Krabbe disease is galactocerebrosidase (GALC)." (PMID 36447271, 2022).
cancer (10 papers, 2013 to 2025). A tumor composed of atypical neoplastic, often pleomorphic cells that invade other tissues. "It has been hypothesized that GALC acts as an oncosuppressor, with its downregulation being a risk factor for developing cancer." (PMID 40391866, 2025). "Still, when sorted by statistical significance, ATG4D, ATAD3A, and MRPL41 are found in less apical positions in the lists of the top 200 genes negatively correlated with GALC expression in the other human cancer data sets investigated here." (PMID 38474307, 2024). "Expression of galactocerebrosidase (GALC), an enzyme that removes galactose from GSLs, is reduced in lung cancer and other human cancers." (PMID 29773994, 2018). "Thus, a contextual relationship appears to exist between GALC expression and mitochondrial plasticity in different human cancers." (PMID 38474307, 2024). "GALC converts GalCer to Cer, while until today, there is no report exploring the association between cancer and GALC in tumor cells." (PMID 34637456, 2021). "They express cancer stem cell markers, such as CD34, MMP2, nestin, and SOX2, as well as the astro-neuronal lineage markers GALC, TUBB3 (CD56), and OLIG2." (PMID 34638987, 2021). "DCTN1, GALC and GALNS also are not known cancer genes in the COSMIC database." (PMID 38310436, 2023).
tumor (9 papers, 2020 to 2025). "It has been proposed that modulation of GALC expression can regulate Cer levels, with its upregulation decreasing Cer levels and promoting tumor cell proliferation." (PMID 40069781, 2025). "High GALC expression can regulate migration during tumor growth by regulating senescent fibroblasts in tumors." (PMID 37168863, 2023). "The diminished progenitor states and potential differentiation of tumor cells were corroborated by the induction of GALC protein expression, another oligodendrocyte maturation marker, in parallel with the reduced level of PDGFRA protein." (PMID 37760589, 2023). "The results demonstrate that senescent fibroblasts with a high level of GALC regulated several aspects of the tumor growth process, including migration and invasion." (PMID 32318333, 2020). "Our data indicate that, besides CD73, GALC transduction induces an increase in the levels of the importin karyopherin subunit alpha 4, kynureninase, and RNA-binding motif protein 12, all involved in tumor immune escape." (PMID 37445731, 2023). "Exogenous administration of ceramide affects the protein profile of different tumor cell types, and the lack of GALC activity alters the proteome of the central and peripheral nervous system in Galc-null Twitcher mice." (PMID 37445731, 2023). "The increased presence of GALC+ and reduced presence of PDGFRA+ cells, together with the mutually exclusive staining pattern of these proteins, suggest these tumor cells indeed became more differentiated upon clemastine treatment." (PMID 37760589, 2023).
neurodegenerative disease (6 papers, 2018 to 2025). A disorder of the central nervous system characterized by gradual and progressive loss of neural tissue and neurologic function. "In conclusion, our research suggests that characterizing GALC gene variants, including the effects of disease‐related polymorphisms or synonymous variants, can be helpful when approaching the diagnostic process of neurodegenerative diseases with unknown etiology and overlapping symptoms of LSDs." (PMID 40391866, 2025). "However, and given the genetic nature of Krabbe disease where toxic substrates of GALC continuously accumulate in the nervous system, ACY-738 did not provide on its own for increased lifespan in this disorder, in contrast to what happens in models of other neurodegenerative diseases." (PMID 37588057, 2023).
infection (5 papers, 2011 to 2024). The state of being infected such as from the introduction of a foreign agent such as serum, vaccine, antigenic substance or organism. "HIV-1 gp120 recognizes CD4 as its main receptor even though it is well known to bind other cell receptors such as the galactocerebroside molecule (GalC) determining a wide array of biological effects from infection of susceptible cells to induction of signal transduction intracellular pathways." (PMID 21612582, 2011). "At 24 h post-infection, cultures were dissociated by papain digestion, and live cells were surface-labeled with anti-GABA, anti-Glast, anti-GalC, and anti-CD68 antibodies targeting neurons, astrocytes, oligodendrocytes, and microglial cells, respectively." (PMID 36680268, 2023). "There was significantly higher frequency of antibodies against GM1, GalNAc‐GD1a, and GM1:GalC complex in patients following C. jejuni infection than patients without infections (P = 0.002, P < 0.001, and P = 0.019, respectively)." (PMID 31714025, 2019).
genetic disease (3 papers, 2022 to 2024). "Globoid cell leukodystrophy (GLD) is an autosomal recessive genetic disease caused by mutations in GALC gene that cause demyelination through lack of galactocerebrosidase activity and ensuing accumulation of β-galactosides and derivatives." (PMID 36247778, 2022).
metabolic disorder (3 papers, 2014 to 2025). "Globoid cell leukodystrophy (GLD) is a metabolic disease caused by mutations in the galactocerebrosidase (GALC) gene." (PMID 25412308, 2014). "Those chronic disorders were related to metabolic disorders and congenital anomalies coded by AGTX, GALC, GRHPR, RDH12, and RPGRIP1L." (PMID 38553482, 2024).
GALC also shares sentences with these, for which no sentence is quoted: Fabry disease (6 papers); Gaucher disease (6); Parkinsonism (3); autosomal recessive disease (2); bipolar disorder (2); depression (2); neurological diseases (2); Niemann-Pick disease (2); oligodendroglioma (2); Primary Open-Angle Glaucoma (2); Wilson disease (2); age-related macular degeneration (1); Aphasia (1); autonomic dysfunctions (1); breast carcinoma (1); breast invasive carcinoma (1); cholangiocarcinoma (1); chronic inflammatory demyelinating polyneuropathy (1); cognitive decline (1); congenital heart disease (1); cystic fibrosis (1); dysautonomia (1); Dystonia (1); endometrial carcinoma (1); erythropoietic protoporphyria (1); esophageal carcinoma (1); Farber lipogranulomatosis (1); Genetic neurodegenerative disease (1); glioblastoma (1); glycine encephalopathy 1 (1).
A further 38 diseases each share a sentence with GALC in 1 paper.